TBL1X (transducin beta like 1 X-linked)
Description:
F-box-like protein involved in the recruitment of the ubiquitin/19S proteasome complex to nuclear receptor-regulated transcription units. Plays an essential role in transcription activation mediated by nuclear receptors. Probably acts as integral component of corepressor complexes that mediates the recruitment of the 19S proteasome complex, leading to the subsequent proteasomal degradation of transcription repressor complexes, thereby allowing cofactor exchange.
Synonyms: TBL1; EBI; CHNG8; SMAP55
Tractability: PROTAC: UniProt records ubiquitination sites on it; ubiquitination databases record sites on it; its protein half-life has been measured.
Gene: Protein-coding gene on chromosome X (9,463,258 to 9,741,037, forward strand). Ensembl gene ENSG00000101849.
Subcellular location: Nucleus
Subcellular location (Human Protein Atlas): Nucleoplasm; Nucleoli
Pathways (Reactome):
Disease: Constitutive Signaling by NOTCH1 HD+PEST Domain Mutants; Constitutive Signaling by NOTCH1 PEST Domain Mutants; HCMV Early Events
Circadian clock: BMAL1:CLOCK,NPAS2 activates circadian expression; Expression of BMAL (ARNTL), CLOCK, and NPAS2; RORA,B,C and NR1D1 (REV-ERBA) regulate gene expression
Gene expression (Transcription): MLL4 and MLL3 complexes regulate expression of PPARG target genes in adipogenesis and hepatic steatosis; Notch-HLH transcription pathway
Metabolism: Activation of gene expression by SREBF (SREBP); PPARA activates gene expression; Regulation of lipid metabolism by PPARalpha
Cellular responses to stimuli: Cytoprotection by HMOX1; Heme signaling
Developmental Biology: Differentiation of naive CD4+ T cells to T helper 2 cells (Th2 cells); Transcriptional regulation of white adipocyte differentiation
Signal Transduction: NOTCH1 Intracellular Domain Regulates Transcription; NR1H3 & NR1H2 regulate gene expression linked to cholesterol transport and efflux
Chromatin organization: HDACs deacetylate histones
Organelle biogenesis and maintenance: Transcriptional activation of mitochondrial biogenesis
Gene Ontology:
Molecular function: histone binding; protein binding; transcription cis-regulatory region binding; transcription corepressor activity
Biological process: negative regulation of transcription by RNA polymerase II; positive regulation of canonical Wnt signaling pathway; positive regulation of DNA-templated transcription; positive regulation of transcription by RNA polymerase II; proteolysis; sensory perception of sound; proteasome-mediated ubiquitin-dependent protein catabolic process; protein stabilization; regulation of transcription by RNA polymerase II
Cellular component: histone deacetylase complex; mitotic spindle; nucleus; transcription repressor complex; nucleoplasm
Homologues: Orthologues: macaque TBL1X (96% identical), chimpanzee TBL1X (87% identical), guinea pig TBL1X (86% identical), mouse Tbl1x (86% identical), rat Tbl1xr1 (86% identical), dog TBL1X (84% identical), tropical clawed frog tbl1x (82% identical), zebrafish tbl1x (75% identical), Drosophila melanogaster ebi (67% identical). Paralogues in human: TBL1Y (83% identical), TBL1XR1 (78% identical).
Diseases named in the same sentence as TBL1X in open-access papers:
TBL1X is named in the same sentence as 34 diseases in open-access papers, as found by Europe PMC text mining. Sharing a sentence is not in itself a finding about the gene and the disease. The quoted sentences say what the papers report.
Central hypothyroidism (4 papers, 2016 to 2021). A type of hypothyroidism due to an insufficient stimulation of an otherwise normal thyroid gland. "Variants in TBL1X have been shown to influence prostate cancer and central hypothyroidism susceptibility." (PMID 30713548, 2018). "A pathogenic role for TBL1X defects is supported by a mouse model in which impaired NCoR function causes central hypothyroidism, and further investigation of the potential role of TBL1X in central hypothyroidism is now needed." (PMID 29026407, 2017). "Recently, mutations in TBL1X have been found in several families with X-linked central hypothyroidism." (PMID 29026407, 2017). "By using DNA-analysis, clinical and biochemical phenotyping, and in vitro functional and expression studies, we show that TBL1X mutations are associated with central hypothyroidism and hearing loss." (PMID 27603907, 2016). "The five genes associated with isolated congenital central hypothyroidism are thyrotropin-releasing hormone receptor gene (TRHR), thyroid-stimulating hormone β-subunit gene (TSHB), and the more recently described genes IGSF1, TBL1X, and IRS4." (PMID 33585976, 2021).
autism (3 papers, 2011 to 2025). Persistent deficits in social interaction and communication and interaction as well as a markedly restricted repertoire of activity and interest as well as repetitive patterns of behavior. "TBL1X is in the Wnt signaling pathway, which has previously been implicated as having a role in autism." (PMID 22050706, 2011). "Multiple studies have shown that deletions in the Xp22.2 to Xp22.3 distal region that contain NLGN4 and TBL1X are associated with autism." (PMID 22050706, 2011). "Among the genes with two hits uniquely in cases were three candidate genes linked to autism by a literature-curated database, DMD, SYNE1, and TBL1X and two genes implicated in schizophrenia (GRIK4) and intellectual disability (PQBP1)." (PMID 26185613, 2015). "Therefore, TBL1X plays a role in pathways that may be critical to the etiology of autism and is an excellent candidate gene." (PMID 22050706, 2011).
autism spectrum disorder (2 papers, 2011 to 2016). A spectrum of developmental disorders that includes autism, and Asperger syndrome. "In a genome-wide association study, TBL1X was identified as a candidate gene for male autism spectrum disorder, but none of present patients had been diagnosed with autism spectrum disorder." (PMID 27603907, 2016).
breast carcinoma (2 papers, 2021 to 2022). "For example, TBL1X promotes EMT of breast cancer cells by acting as a cofactor of ZEB1 to regulate the expression of CDH1, and the high expression of TBL1X contributes to metastasis of breast cancer and is correlated with the poor prognosis of patients with breast cancer." (PMID 35173544, 2022).
diabetes (2 papers, 2023 to 2026). "We identify the transcriptional co-factors transducin β-like 1 x-linked (TBL1X) and its homolog TBL1X-related (TBL1XR1, together TBL/R1) as crucial regulators of β-cell identity and determinants of diabetes development and progression." (PMID 42020373, 2026). "Interestingly, C12orf43, TBL1X and TNKS were significantly associated with diabetes or hypertension-related phenotypes in the UK Biobank." (PMID 37239390, 2023).
hearing loss (2 papers, 2016 to 2020). "In conclusion, we demonstrate that mutations in TBL1X are associated with CeH and hearing loss." (PMID 27603907, 2016). "Mutations in LOXHD1, OTOF, PCDH15, TBL1X, and TMC2 have been associated with hereditary disorders of balance, deafness or hearing loss in humans (NCBI gene db and GeneCards)." (PMID 32770228, 2020). "In humans, TBL1X deletions have been associated with hearing loss but not with CeH." (PMID 27603907, 2016).
Intellectual disability (2 papers, 2011 to 2015). "Deletions in the Xp22.2 to Xp22.3 region containing TBL1X and surrounding genes are associated with several genetic syndromes that include intellectual disability and autistic features." (PMID 22050706, 2011).
nasopharyngeal carcinoma (2 papers, 2022 to 2024). A carcinoma arising from the nasopharyngeal epithelium. "TBL1X could reestablish the functional changes of nasopharyngeal carcinoma cells by Flot2 alteration." (PMID 39390002, 2024). "TBL1X promoted nasopharyngeal carcinoma cell migration and invasion through Flot2." (PMID 39390002, 2024). "TBL1X and Flot2 have the same direction of regulation in nasopharyngeal carcinoma." (PMID 39390002, 2024). "In addition, nasopharyngeal carcinoma patients with high TBL1X expression had a poor prognosis." (PMID 39390002, 2024). "We showed TBL1X expression was amusing higher in metastatic nasopharyngeal carcinoma tissues compared to non-metastatic tissues and correlated with TNM stage and metastasis of nasopharyngeal carcinoma patients." (PMID 39390002, 2024).
ocular albinism with late-onset sensorineural deafness (2 papers, 2011 to 2025). "For example, Lis1 plays a role in lissencephaly, TCOF1 is associated with Treacher Collins Syndrome (TCS), and TBL1X participates in Ocular Albinism with late-onset sensorineural deafness (OASD)." (PMID 41312386, 2025). "Furthermore, TBL1X is partially or completely deleted in patients with the ocular albinism with late-onset sensorineural deafness (OASD) gene [OMIM:300650] carrying Xp22.3-terminal deletions." (PMID 22050706, 2011).
atherosclerosis (1 paper, 2026). A disease characterized by the build-up of fatty material and calcium deposition in the arterial wall resulting in partial or complete occlusion of the arterial lumen. "Restoration of TBL1X/TBL1XR1 functionality may thus serve as a novel, druggable strategy for preventing or limiting atherosclerosis progression." (PMID 41539423, 2026).
Hypercholesterolemia (1 paper, 2016). An increased concentration of cholesterol in the blood. "Because 6 of 17 had hypercholesterolemia, at this point we cannot exclude that hypercholesterolemia is part of the TBL1X mutation phenotype." (PMID 27603907, 2016).
hypertriglyceridemia (1 paper, 2016). A laboratory test result indicating elevated triglyceride concentration in the blood. "In mice, loss of hepatic TBL1X was found to result in hepatic hypertriglyceridemia and steatosis." (PMID 27603907, 2016).
hypopituitarism (1 paper, 2025). A condition of diminution or cessation of secretion of one or more hormones from the anterior pituitary gland. "There are many causative genes for its isolated form or for multihormonal hypopituitarism, such as TSHβ, TRHR, TBL1X and IRS4 (for heritable isolated central hypothyroidism) and PROP1, HESX1, SOX3 (for multihormonal hypopituitarism)." (PMID 39997750, 2025).
hypothyroidism (1 paper, 2016). Abnormally low levels of thyroid hormone. "An important question is whether the lowered plasma FT4 concentrations in individuals with TBL1X mutations, especially in those biochemically classified as having CeH, result in hypothyroidism at the level of TH target tissues." (PMID 27603907, 2016).
Rett syndrome (1 paper, 2018). A severe neurodevelopmental disorder affecting the central nervous system. "While it is conceivable that TBL1X(R1) is involved in additional functional complexes that are relevant to Rett syndrome, none has so far been characterized." (PMID 30463906, 2018).
tumor (8 papers, 2012 to 2026). "To investigate the potential molecular mechanisms underlying the functions of TBL1X in NPC, we classified all tumor samples into high and low expression groups based on the median of TBL1X expression in the TCGA datasets." (PMID 35173544, 2022). "This reversal in correlation direction was unique to RIGI and TBL1X; the other five proteins maintained consistent patterns with the DEGs across tumor types (p < 0.05), suggesting a context-dependent shift in regulatory relationships during tumor progression." (PMID 41596598, 2026). "Both LRP6 and TBL1X are found to function as oncogenes during tumor progression." (PMID 25491321, 2014). "We next assessed whether the aberrant chromatin status of the Xi also translated into X-linked gene reactivation by assessing XIST together with HDAC8, ATRX, MAGEA6, and TBL1X expression on fresh tumor stamps (including those analyzed above) or tumor-tissue cryosections." (PMID 25653311, 2015). "A similar study has shown that TBL1X suppresses E-cadherin expression by interacting with TWIST, thereby promoting tumor metastasis." (PMID 35173544, 2022). "The results demonstrated that TBL1X expression was significantly different in 13 types of tumors compared to their relative normal tissues, with higher expression of TBL1X in six types of cancers, including HNSC, and lower expression in the other seven types of tumor tissues." (PMID 35173544, 2022). "In primary HGSOC, the recurrent tumor-specific DEG IL7R exhibited a positive correlation with AMBP and HDGF and a negative correlation with FEN1, LRRC25, RIGI, and TBL1X (p < 0.05)." (PMID 41596598, 2026).
cancer (5 papers, 2013 to 2022). A tumor composed of atypical neoplastic, often pleomorphic cells that invade other tissues. "Firstly, we carried out a pan-cancer analysis to investigate the expression of TBL1X in different cancer types and their corresponding normal tissues using TCGA datasets." (PMID 35173544, 2022). "TBL1X has been shown abnormally expressed in diverse cancers." (PMID 35173544, 2022). "We then investigated the degree to which reactivation could impact on gene dosage for TBL1X, one of the “cancer-specific” escapees in ZR-75-1 cells." (PMID 25653311, 2015). "However, we noted that some genes subject to XCI (i.e., only expressed from the Xa) in cancer cell lines, nevertheless showed low promoter methylation (e.g., TBL1X in SK-BR-3 cells or HDAC8 in ZR-75-1)." (PMID 25653311, 2015). "For “cancer-specific” escapees (TBL1X in ZR-75-1, HDAC8 in MDA-MB-436 and SK-BR-3), no obvious systematic correlation between local H3K27me3 levels and escape/silencing could be seen." (PMID 25653311, 2015).
TBL1X also shares sentences with these, for which no sentence is quoted: breast tumors (2 papers); albinism (1); breast invasive carcinoma (1); central congenital hypothyroidism (1); colon adenocarcinoma (1); deafness (1); esophageal carcinoma (1); glioblastoma multiforme (1); Hypertension (1); Insulin resistance (1); Lissencephaly (1); Obesity (1); ocular albinism (1); prostate carcinoma (1); schizophrenia (1); steatosis (1); Treacher-Collins syndrome (1).